TLR2 (toll like receptor 2)
Diseases named in the same sentence as TLR2 in open-access papers (continued):
Sharing a sentence is not in itself a finding about the gene and the disease.
diabetes (continued). "The goal of the study was an analysis of the expression and functional activity of TLR2 and TLR4 on the cells of peripheral blood of patients with bronchial asthma (BA), type 2 diabetes mellitus (T2DM), and a combination of both diseases (BA + T2DM)." (PMID 36836906, 2023). "Similar to TLR4, Toll-like receptor 2 (TLR2) also triggers inflammation while promoting pancreatic beta-cells dysfunction and diabetes development." (PMID 37299482, 2023). "In this study, the percentage and number of selected lymphocytes expressing TLR2, TLR4, and TLR9 receptors in children with type 1 diabetes mellitus were assessed." (PMID 34830017, 2021). "For instance, vitD decreased expression of TLR2 and TLR4 on the monocytes of the patients suffering from type 2 diabetes mellitus and latent autoimmune diabetes." (PMID 35126351, 2021). "Tlr2 and Pycard are up-regulated in NOD ES cells, which is consistent with previous reports on their involvement in inflammation and diabetes." (PMID 32796510, 2020). "In the GC group, there was a significant correlation between duration of diabetes and monocyte RANTES (r = −0.715, p = 0.05) and TLR8 (r = 0.741, p = 0.04) mRNA, and neutrophil TLR2 mRNA (r = −0.838, p = 0.01)." (PMID 28794498, 2017). "To determine the role of TLR2 and 4 in the pathogenesis of microangiopathy, we assessed for ICAM-1 expression in TLR2-/- and TLR4-/- murine models after the induction of diabetes." (PMID 25303153, 2014). "TLR2 and TLR4 play an important role in diabetic nephropathy, and especially in the high-fat diet-induced diabetes rat model, TLR4 and its downstream IKKβ/NF-κB pathway components are significantly activated." (PMID 24810370, 2014). "Deletion of MyD88 from only marrow-derived cells totally inhibited the endothelial ICAM-1 induction in retinas from diabetic animals, and signaling through both TLR2/4 and IL-1β contributed partially to altered regulation of ICAM-1 in diabetes." (PMID 23874797, 2013). "Taken together, these observations suggest a potential role for TLR2 and TLR4 in the pathology of diabetes." (PMID 22219634, 2011). "Surprisingly, NOD DCs treated with the TLR2 agonist, lipoteichoic acid (LTA) produced large amounts of IL-12 and accelerated diabetes onset and increased disease incidence upon transfer into NOD mice." (PMID 21716731, 2011). "Another study showed that mice with diabetes have higher levels of toll‐like receptor 2 (TLR‐2) when compared to mice without diabetes when measuring TLR‐2 mRNA and protein expression, and increased TLR‐2 was found to inhibit wound healing." (PMID 40888511, 2025). "Diabetes is also characterized by inflammation, as well as increased serum levels of high-mobility group box 1 (HMGB1) protein, an endogenous protein reported to activate toll-like receptors (TLRs), such as TLR2 and TLR4." (PMID 36674890, 2023). "A recent study showed that oxidative stress (ROS and H2O2) promoted the expression of Toll-like receptor 2 (TLR2) and Toll-like receptor 4 (TLR4) in human periphery monocytes to increase the expression of cytokines, such as IFN−gamma, IL−1 beta, IL−6, etc., in diabetes mellitus (DM)." (PMID 37175958, 2023). "Finally, TLR2- and TLR4-induced expression of immunomodulatory effectors Cox-2 and IDO was significantly augmented by diabetes." (PMID 34566972, 2021). "In the present study, we investigated the influence of TLR2 on immune-related events in experimental deep dermatophytosis using diabetic and non-diabetic mouse models, since diabetes mellitus patients are also affected with this fungal infection." (PMID 28164040, 2017). "Moreover, in TLR2-/- and TLR4-/- mice induced with diabetes, there was an amelioration of glomeruli ICAM-1 expression versus wildtype diabetic mice." (PMID 25303153, 2014). "Moreover, we have uniquely shown that there is a marked reduction in glomerular ICAM-1 expression in TLR2-/- and TLR4-/- murine models compared to wildtype mice induced with diabetes." (PMID 25303153, 2014).
diabetes (continued). "This suggests that inhibition of leukocyte mediated killing of endothelial cells in animals lacking TLR2/4 is mediated via a MyD88-independent pathway, but clearly indicates that MyD88 is a factor in diabetes-induced leukocyte activation." (PMID 23874797, 2013). "Since white blood cells play causal roles in the development of diabetic retinopathy, the present study investigates MyD88-dependent processes (involving TLR2/TLR4 and IL-1ß) in leukocytes from diabetic mice, and how these changes affect leukocyte-endothelial interactions in the retina in diabetes." (PMID 23874797, 2013). "Our findings suggest that TLR2 activation and AGEs may be beneficial for wound healing and skin hydration under normal conditions via AQP3 upregulation, but that these pathways are likely deleterious in diabetes chronically through decreased AQP3 expression." (PMID 36674890, 2023). "These authors used a model of diabetes induced using the drug streptozotocin and identified decreased NFkB and MyD88 activity, along with IRAK-1 phosphorylation, leading to a decrease in circulating chemokines and cytokines in TLR2−/−, compared with wild-type, mice." (PMID 28164040, 2017). "We and others have shown increased pattern recognition receptors, TLR2 and TLR4, in diabetes and have also shown that knockout of TLR2 and/or TLR4 in a mouse model can result in decreased microvascular complications using the streptozotocin- (STZ-) induced diabetes model." (PMID 29435463, 2017). "However, data examining the mechanism of TLR2 and TLR4 expression and function of cornea in diabetes are unknown." (PMID 22219634, 2011). "While TLR2 and TLR9 knockout mice show little development of diabetes, a defect of TLR3 appears to be without impact and, as we show here, deficiency in TLR4 causes enhancement of the disease process." (PMID 24086519, 2013).
Insulin resistance (77 papers, 2009 to 2025). Increased resistance towards insulin, that is, diminished effectiveness of insulin in reducing blood glucose levels. "Other studies have similarly reported that TLR2-deficient mice show improved insulin sensitivity and enhanced hepatic insulin signaling and are protected from high-fat diet-induced insulin resistance and pancreatic beta cell dysfunction." (PMID 40558558, 2025). "Other studies also demonstrated that SFAs indeed can activate Toll-like receptor 4-(TLR4-) and TLR2-mediated pro-inflammatory signaling pathways and consequently increase the risk of insulin resistance." (PMID 37901107, 2023). "In mice, it is known that TLR-2 deficiency confers protection against insulin resistance and also reduces HFD-induced tissue inflammation, in a process dependent on the host microbiota." (PMID 35335996, 2022). "Activation of the TLR2 signaling pathway has been reported to be associated with chronic inflammation, which triggers the development of insulin resistance in adipocytes." (PMID 36501080, 2022). "With respect to inflammation, TLR4 and TLR2 activation by saturated FFA also causes insulin resistance, potentially via JNK in skeletal muscle." (PMID 32183037, 2020). "TLR2 and 4 have been implicated in fat-induced hepatic and peripheral insulin resistance and β-cell dysfunction." (PMID 32183037, 2020). "Now, in this issue of PLoS Biology, Andréa Caricilli and colleagues present compelling evidence that gut bacteria can nullify the genetic protection against insulin resistance in TLR2-deficient mice." (PMID 22162951, 2011). "This suggests that the Firmicutes-rich gut bacteria from these TLR2-deficient mice were enough to cause insulin resistance." (PMID 22162951, 2011). "The underlying mechanisms that may lead to insulin resistance could involve an eHSP70-mediated stimulation of the TLR2/4." (PMID 36291584, 2022). "A previous study showed that TLR2 activation could cause ER stress, inflammation, and insulin resistance." (PMID 32536938, 2020). "Toll-like receptor 2 (TLR2) knockout mice exhibit insulin resistance and glucose intolerance associated with key modifications in intestinal microbiota, including higher proportions of Bacteroidetes and Firmicutes coupled with a lower proportion of Proteobacteria phyla." (PMID 31182162, 2019). "Importantly, inhibition of TLR2 signaling prevents insulin resistance in HFD mice, whereas TLR2-deficient mice fed HFD display reduced levels of inflammatory cytokines and do not develop NASH." (PMID 27657051, 2016). "The TLR2-deficient mice got much fatter and glucose tolerance tests revealed that they also developed diabetes, indicating that the high-fat diet exacerbated their insulin resistance." (PMID 22162951, 2011). "Insulin resistance can be caused by bacterial cell membrane compounds called lipopolysaccharides, and several lines of evidence suggest that this is a likely mechanism for the development of insulin resistance in the TLR2-deficient mice studied." (PMID 22162951, 2011). "Conversely, eHSP70 can act as a DAMP and activate TLR2/4-mediated pro-inflammatory responses leading to insulin resistance and β-cell dysfunction." (PMID 41488136, 2025). "Some metabolic complications, such as insulin resistance and β-cell dysfunction, are related to the overexpression of TLR2 and TLR4 in patients with obesity and DM." (PMID 40076851, 2025). "In patients with T2DM, the increased expression of TLR2, TLR4, and plasma LPS is associated with plasma insulin concentration and insulin resistance." (PMID 40076851, 2025). "Most interestingly, it was shown that a HFD promotes certain adipocytes to co-express toll-like receptor 2 (TLR2) and its downstream molecule, TNFα to induce insulin resistance in mice in the presence of free fatty acids (FFA)." (PMID 37445827, 2023). "PUFA improves insulin resistance through suppression of TLR2/4 signaling and activation of PPAR signaling." (PMID 37960324, 2023).
Insulin resistance (continued). "Inflammation has been shown to be a component of type 2 DM triggered through Toll-like receptor (TLR-2) signaling, in conjunction with free radical production, which is correlated with insulin resistance." (PMID 36903646, 2023). "Our studies in mice show that TLR2 plays a fundamental role in the regulation of adipocyte differentiation and hypertrophy, insulin resistance, and glucose tolerance under normal diet conditions." (PMID 36555322, 2022). "As knockout Toll-like receptor 2 (TLR2) is attributed to induce insulin resistance and glucose intolerance in mice, it reveals a mechanism of disruption of insulin sensitivity by inflammation via TLR signaling cascade." (PMID 36556351, 2022). "Many studies claimed that TLR2−/− mice were substantially protected from diet-induced adiposity and insulin resistance." (PMID 36555322, 2022). "Whereas some groups have reported that inhibiting TLR2 confers protection to insulin resistance and DIO in mice, other studies point to the exact opposite." (PMID 36555322, 2022). "This study identified a component of the A. muciniphila outer membrane protein-AMUC_1100 (which interacts with TLR2) that plays a role in reducing fat development, insulin resistance, and dyslipidemia in mice after pasteurization." (PMID 36439840, 2022). "• T cell activation. • Induction of inflammatory molecules like IL8, IL12A, CCL5, CCL19, CCR2, and CCR5. • Contribution to increased insulin resistance secondary to TLR2, TLR4, and TLR10 interaction." (PMID 35422689, 2022). "On the opposite, apoC3 appears as pro-diabetic by triggering pancreatic beta-cell apoptosis and by promoting insulin resistance via Toll-Like Receptor 2 (TLR2) activation in transgenic mouse models." (PMID 36471375, 2022). "TLR2 expression is increased in the muscle and adipose tissue of HFD mice, and TLR2 gene silencing improves insulin resistance in these mice." (PMID 36501080, 2022). "In particular, activation of Toll-like receptor (TLR)-2 and TLR-4 is associated with obesity-mediated insulin resistance and the pathogenesis of metabolic diseases." (PMID 34832960, 2021). "In a mouse model, oral administration of Akkermansia activated toll-like receptor 2, increased the expression of epithelial tight-junction proteins, and reversed high-fat diet-induced insulin resistance." (PMID 36713356, 2021). "For insulin resistance, β-cell dysfunction by saturated fat was prevented in TLR2- and TLR4-null mice, and in NLRP3-null mice." (PMID 32183037, 2020). "Innate immunity receptors potentially activating JNK participate in hepatic lipotoxicity, as shown by protection from hepatic insulin resistance by TLR2 or 4 KO." (PMID 32183037, 2020). "By contrast, mice with Tlr2 lesions derived from a different founder strain (Tlr2tm1Kir) demonstrated hyperphagia, enhanced glucose tolerance, decreased insulin resistance and decreased RER on a high fat diet compared to controls." (PMID 28769782, 2017). "TLR2 KO mice are substantially protected from diet-induced adiposity, insulin resistance, hypercholesterolemia and hepatic steatosis." (PMID 24064574, 2013). "The insulin resistance of TLR2 KO mice was accompanied by a down-modulation of insulin-induced insulin signaling in the liver, muscle, and adipose tissue, associated with an increase in endoplasmic reticulum stress." (PMID 23482058, 2013). "Other studies have reported that TLR2 knockout (KO) mice present decreased body weight and adiposity, are protected against insulin resistance, and gain less weight on a HFD than control mice and are also protected against related comorbidities." (PMID 23482058, 2013). "The close relationship between increased TLR-2 expression in blood monocytes and insulin resistance in RA patients is shown in this study." (PMID 23213270, 2012).
Insulin resistance (continued). "The reduction in the expression of adiponectin receptors in response to TLR2 activation with peptidoglycan also agrees with the finding that these receptors are downregulated in adipose tissue of obese and insulin resistant mice." (PMID 19348674, 2009). "Together, these results point to the fact that macrophages are the first immune cells to infiltrate AT inducing ECM remodeling, which may be instrumental in insulin resistance development through the TLR2/Myd88/NFκB pathway." (PMID 37445827, 2023). "Similarly, TLR2 knockout mice had differences in the gut microbiota compared with wild-type mice, and exhibited glucose intolerance and insulin resistance." (PMID 35242721, 2022). "Saturated fatty acids trigger insulin resistance by activating TLR-2 and TLR-4." (PMID 34832960, 2021). "JZG may regulate CD14/TLR4 and TLR2 signaling pathways, improving inflammation and insulin resistance targeted at gut microflora." (PMID 34966475, 2021). "These associations reflect the roles of TLR2 and TLR4 in the progress of insulin resistance and inflammation which in turn may lead the advance of nephrotic disease to the end-renal disease stage and renal failure." (PMID 33442388, 2020). "In addition, TLR2-deficient mice are protected from HFD-induced adiposity, insulin resistance, impaired insulin secretion, and hypercholesterolemia." (PMID 31582899, 2019). "Interestingly, it has been shown that oral administration of A. muciniphila improves glucose tolerance and insulin resistance, and reduces adipose tissue inflammation in mice, possibly via Toll-like receptor 2 signalling." (PMID 29379988, 2018). "Notably, high fat diet fed TLR2−/− mice were found to be protected from insulin resistance and β-cell dysfunction." (PMID 26312071, 2015). "The insulin resistance in TLR2 KO mice could be explained by the increased LPS serum levels, which lead to TLR4 activation in the insulin target organs." (PMID 24064574, 2013). "Overall, TLR2 could be a key modulator between inflammatory pathways and metabolic disorders such as insulin resistance." (PMID 23213270, 2012). "This study may lead to a better understanding of the relationship between TLR2 expression and insulin resistance in patients with RA." (PMID 23213270, 2012). "This investigation tests the hypothesis that expressions of TLR2 or TLR4 on monocytes and related inflammatory cytokines, such as TNF-α and IL-6, might be associated with insulin resistance in patients with RA." (PMID 23213270, 2012). "Genetic analysis of their gut bacteria revealed that the abundance of Firmicutes was three times higher than that of wild-type mice, and the researchers suggest that this explains why these TLR2-deficient mice were not protected against insulin resistance." (PMID 22162951, 2011). "Furthermore, treatment with alpha-lipoic acid and metformin has been shown to improve insulin resistance and cognitive deficits by modulating TLR2 signaling, further supporting the involvement of TLR2-driven inflammation in metabolic dysfunctions and their neurological consequences." (PMID 40558558, 2025). "In the present study, higher expression of TLR2 and TLR4 in diabetic patients with kidney failure than in diabetic patients without kidney failure was associated with higher values of HOMA-IR (as indicator of insulin resistance) and lower values of HOMA-IS (as indicator of insulin sensitivity)." (PMID 33442388, 2020). "Moreover, TLR2 and TLR4 activity was markedly increased in association with elevated TNF-α, IL-6, and IFN-γ expressions, increased insulin resistance in response to inflammation; the changes were more prominent in diabetic patients with end-stage renal disease and renal failure." (PMID 33442388, 2020). "Insulin resistance associated with absent TLR2 signaling may be attributed to increased serum lipopolysaccharide (LPS) activation of toll-like receptor 4 (TLR4) in the muscle, liver, and adipose tissue." (PMID 31182162, 2019).